SLC25A33 (solute carrier family 25 member 33)
Description:
Mitochondrial transporter that imports/exports pyrimidine nucleotides into and from mitochondria. Selectively transports uridine, thymidine, guanosine, cytosine and inosine (deoxy)nucleoside di- and triphosphates by an antiport mechanism. May import (deoxy)nucleoside triphosphates in exchange for intramitochondrial (deoxy)nucleoside diphosphates, thus providing precursors necessary for de novo synthesis of mitochondrial DNA and RNA while exporting products of their catabolism. Participates in mitochondrial genome maintenance, regulation of mitochondrial membrane potential and mitochondrial respiration. Upon INS or IGF1 stimulation regulates cell growth and proliferation by controlling mitochondrial DNA replication and transcription, the ratio of mitochondria-to nuclear-encoded components of the electron transport chain resulting in control of mitochondrial ROS production. Participates in dendritic cell endocytosis and may associate with mitochondrial oxidative phosphorylation.
Synonyms: BMSC-MCP; MGC4399; PNC1
Tractability: Antibody: UniProt predicts a signal peptide or a membrane-spanning region. PROTAC: its protein half-life has been measured.
Gene: Protein-coding gene on chromosome 1 (9,539,465 to 9,585,173, forward strand). Ensembl gene ENSG00000171612.
Subcellular location: Mitochondrion inner membrane
Gene Ontology:
Molecular function: pyrimidine nucleotide transmembrane transporter activity
Biological process: cellular response to insulin stimulus; cellular response to insulin-like growth factor stimulus; mitochondrial respiratory chain complex III assembly; mitochondrial transcription; mitochondrion organization; positive regulation of cell growth; positive regulation of cell population proliferation; pyrimidine nucleotide import into mitochondrion; regulation of oxidative phosphorylation; regulation of reactive oxygen species biosynthetic process; mitochondria-nucleus signaling pathway; nucleotide transport
Cellular component: mitochondrion; mitochondrial membrane; mitochondrial inner membrane
Genetic constraint (gnomAD): Loss-of-function variants: 15 observed, 31.12 expected, observed/expected ratio (o/e) 0.48, 90% interval 0.32 to 0.74. The upper end of that interval is the gene's LOEUF score, 0.74, which puts it in group 3 of 6, group 1 being the genes least tolerant of losing a copy. Missense variants: 255 observed, 387.25 expected, observed/expected ratio (o/e) 0.66, 90% interval 0.59 to 0.73. Synonymous variants: 136 observed, 147.09 expected, observed/expected ratio (o/e) 0.92, 90% interval 0.8 to 1.07.
Homologues: Orthologues: chimpanzee SLC25A33 (99% identical), dog SLC25A33 (97% identical), pig SLC25A33 (96% identical), guinea pig SLC25A33 (94% identical), mouse Slc25a33 (91% identical), rabbit SLC25A33 (91% identical), rat Slc25a33 (91% identical), zebrafish slc25a33 (75% identical). Paralogues in human: SLC25A36 (59% identical), SLC25A12 (26% identical), SLC25A13 (25% identical), SLC25A28 (24% identical), SLC25A25 (24% identical), SLC25A23 (23% identical), SLC25A24 (22% identical), SLC25A37 (22% identical), SLC25A32 (22% identical), SLC25A5 (22% identical), SLC25A31 (21% identical), SLC25A4 (21% identical), and 37 more.
Diseases named in the same sentence as SLC25A33 in open-access papers:
SLC25A33 is named in the same sentence as 24 diseases in open-access papers, as found by Europe PMC text mining. Sharing a sentence is not in itself a finding about the gene and the disease. The quoted sentences say what the papers report.
breast carcinoma (5 papers, 2020 to 2024). "Research has found that the gene for the SLC25A43 mitochondrial transporter is commonly deleted in HER2+ breast cancer, as well as in other cancers, and altered SLC25A33 expression influences the proliferation of breast cancer cells." (PMID 32455902, 2020).
Alzheimer disease (1 paper, 2025). A progressive, neurodegenerative disease characterized by loss of function and death of nerve cells in several areas of the brain leading to loss of cognitive function such as memory and language. "In Alzheimer's disease, the hub genes TNFRSF9, LZIC, CD30, SLC45A1, GPR157, and SLC25A33 are implicated in immune regulation, cellular transport, neuronal signaling, and mitochondrial function." (PMID 40104076, 2025).
endothelial dysfunction (1 paper, 2025). In vascular diseases, endothelial dysfunction is a systemic pathological state of the endothelium (the inner lining of blood vessels) and can be broadly defined as an imbalance between vasodilating and vasoconstricting substances produced by (or acting on) the endothelium. "The top hub genes identified were TNFRSF9, LZIC, TNFRSF8, SLC45A1, GPR157, and SLC25A33, which are induced by P. gingivalis and F. nucleatum and are responsible for endothelial dysfunction in brain cells." (PMID 40104076, 2025). "The top hub genes were TNFRSF9, LZIC, TNFRSF8, SLC45A1, GPR157, and SLC25A33, induced by P. gingivalis and F. nucleatum responsible for endothelial dysfunction in brain cells." (PMID 40104076, 2025). "Similarly, our study revealed genes like TNFRSF9, LZIC, TNFRSF8, SLC45A1, GPR157, and SLC25A33 that contribute to endothelial dysfunction in brain cells due to P. gingivalis and F. nucleatum." (PMID 40104076, 2025).
hearing loss (1 paper, 2022). "Other genes were related to BPD-associated outcomes such as retinopathy of prematurity (ROP, e.g., GBP3, FJX1, HIPK2) and hearing loss (e.g., GJB6, TMEM63B) and mitochondrial energy metabolism (e.g., TOMM7, SLC25A26, SLC25A33, PDK1, PKM, MDH1)." (PMID 35484630, 2022).
liver abscesses (1 paper, 2025). "Importantly, increased SLC25A33 expression in blood monocytes from septic patients with liver abscesses support the significance of this protein in systemic inflammation." (PMID 40384854, 2025). "Subsequently, we measured the mRNA expression of SLC25A22, SLC25A33, and SLC25A37, along with that of pro-inflammatory cytokines, including TNF-α, IL-6, and IL-1β, in CD14+ monocytes from sepsis patients with liver abscesses." (PMID 40384854, 2025).
periodontal disease (1 paper, 2025). "SLC25A33, a mitochondrial transporter, plays a role in cellular energy metabolism and may contribute to periodontal disease pathology." (PMID 40104076, 2025).
Sepsis (1 paper, 2025). Sepsis is defined as life-threatening organ dysfunction caused by a dysregulated host response to infection. "These collective findings support a pivotal role of SLC25A33 in modulating macrophage polarization and the progression of sepsis in mice." (PMID 40384854, 2025). "To determine the role of SLC25A33 in macrophages during sepsis, we depleted macrophages from mice via intravenous CL injections, before reintroducing SLC25A33-silenced BMDMs using three distinct clones of SLC25A33 shRNA." (PMID 40384854, 2025). "Together, these data demonstrate a significant upregulation of SLC25A33 in LPS/IFN-γ-stimulated macrophages and CD14+ monocytes from human sepsis, suggesting a potential role for SLC25A33 in dysregulated inflammatory responses." (PMID 40384854, 2025). "The inflammatory functions of SLC25A33 were consistently observed across both in vitro and in vivo sepsis models." (PMID 40384854, 2025). "SLC25A33 expression was significantly elevated in CD14+ monocytes derived from patients with sepsis and LPS/interferon-gamma (IFN-γ)-stimulated peritoneal macrophages (PMs)." (PMID 40384854, 2025). "In conclusion, the data presented herein demonstrate that LPS-induced overexpression of SLC25A33 triggers mtDNA synthesis and cytosolic release, thereby demonstrating that SLC25A33 has a pivotal role in the inflammatory response of M1 macrophages during sepsis." (PMID 40384854, 2025). "In our LPS-induced sepsis model, the CL-treated mice reconstituted with SLC25A33-silenced BMDMs exhibited a higher survival rate and decreased secretion of pro-inflammatory cytokines, such as TNF-α, IL-6, and IL-1β, relative to mice reconstituted with vehicle-treated BMDMs." (PMID 40384854, 2025). "We also determined whether downregulation of SLC25A33 could modulate M1 polarization of macrophages and limit dysregulated inflammatory responses and the severity of sepsis." (PMID 40384854, 2025). "Furthermore, the expression of SLC25A33 in CD14+ monocytes, which correlates with pro-inflammatory cytokine production and clinical resolution in sepsis patients, underscores the clinical significance of SLC25A33 in macrophage-mediated inflammatory diseases." (PMID 40384854, 2025). "Notably, the elevated expression of SLC25A33 and cytokines decreased after the patients recovered from sepsis." (PMID 40384854, 2025). "Our findings underscore the significant role of SLC25A33 in inflammation, suggesting that targeting of SLC25A33 could be a promising therapeutic strategy for the management of M1 macrophage-mediated inflammatory diseases, including sepsis." (PMID 40384854, 2025). "We employed LPS-induced septic shock models, both with and without reconstitution with SLC25A33-silenced BMDMs, alongside a CLP-induced sepsis model, to examine the role of SLC25A33 in the inflammatory responses in vivo." (PMID 40384854, 2025).
cancer (8 papers, 2016 to 2025). A tumor composed of atypical neoplastic, often pleomorphic cells that invade other tissues. "Interestingly, suppression of PNC1/SLC25A33 expression in cancer cell lines causes a profound mitochondrial dysfunction, an increase in ROS and an induction of the Epithelial Mesenchymal Transition (EMT)." (PMID 31936236, 2020). "Among these proteins, we have identified many differentially abundant proteins identified as having a role in cancer (IFIT1, FASTKD2, PIP4K2B, ARID1B, SLC25A33: overexpressed in TR; CALD1, CPA3, B3GALT5, CD177, RIPK1: overexpressed in NR)." (PMID 29681787, 2018). "We have identified many differentially abundant proteins already identified as having a role in cancer, such as the earlier discussed proteins IFIT1, FASTKD2, PIP4K2B, ARID1B and SLC25A33 (more abundant in TR) or CALD1, CPA3, B3GALT5, CD177 and RIPK1 (more abundant in NR)." (PMID 29681787, 2018). "Six genes (SLCO2A1, MGAT4B, SLC25A33, MCCC1, OIP5, and CTHRC1) have been shown to affect the tumorigenesis of other cancer types but not PC." (PMID 30024105, 2018).
SLC25A33 also shares sentences with these, for which no sentence is quoted: infection (3 papers); hepatocellular carcinoma (2); tumor (2); abdominal aortic aneurysm (1); cervical cancer (1); cholelithiasis (1); Hepatic steatosis (1); lung carcinoma (1); myocardial hypertrophy (1); neurodegenerative disease (1); Obesity (1); retinal disease (1); retinopathy of prematurity (1); spinocerebellar ataxia (1); Stillbirth (1); Stroke (1).